MYCN (MYCN proto-oncogene, bHLH transcription factor)
Diseases named in the same sentence as MYCN in open-access papers (continued):
Sharing a sentence is not in itself a finding about the gene and the disease.
neuroblastoma (continued). "RA was not an effective treatment option for neuroblastoma patients with MYCN amplification because MYCN amplification caused RA treatment resistance." (PMID 37375824, 2023). "Treatment for NB is decided according to the International Neuroblastoma Risk Group (INRG) stratification, which combines the following criteria: INRG stage, age, histology, tumor differentiation grade, MYCN amplification status, presence of chromosomal aberration, and tumor cell ploidy." (PMID 36765874, 2023). "Considering EZH2 as a potential epigenetic repressor of RUNX3, there could be a regulatory mechanism for the MYCN protein by mutually exclusive binding to oncogenic EZH2 or tumor-suppressive RUNX3 in neuroblastomas." (PMID 36831211, 2023). "Finally, we demonstrated that an antimitotic/pro-apoptotic targeted combination therapy was synergistic against MYCN, making them efficacious in cell lines and animal models of neuroblastoma." (PMID 37958555, 2023). "In neuroblastoma — a pediatric malignancy originating from neural crest–derived progenitor cells — neuroblasts fail to differentiate while transforming to a malignant cell state, often driven by aberrant high-level expression of MYCN or MYC." (PMID 37183825, 2023). "Overexpression of MYCN sensitises neuroblastoma cells to redox stress and lipid peroxidation upon cysteine limitation, triggering ferroptotic (iron-dependent) cell death, and exposing another metabolic liability in these tumours that was capitalised on by targeting cysteine import and/or metabolism." (PMID 37414143, 2023). "All of these indicates that MYCN signaling is crucial in maintaining an undifferentiated phenotype, and MYCN can be used as one of the basis and evaluation indicators for the application of 13-cis RA-induced differentiation treatment for neuroblastoma." (PMID 37745860, 2023). "MYCN is a marker closely related to neuroblastoma proposed in recent years." (PMID 37592273, 2023). "The MYCN gene in neuroblastoma subsets continues to present a significant challenge." (PMID 37274289, 2023). "They carry a normal MYCN, neuroblastoma oncogene, copy number and hyperdiploid DNA index." (PMID 40041269, 2023). "In vitro assays using human neuroblastoma cells showed that 191Pt-MYCN-PIP bound to DNA efficiently and caused DNA damage, decreasing MYCN gene expression and MYCN signals in in situ hybridization analysis, as well as cell viability, especially in MYCN-amplified Kelly cells." (PMID 38004392, 2023). "Radiomic signatures of 18F-FDG-based PET/CT can predict MYCN amplification in neuroblastoma." (PMID 38001240, 2023). "A 26-month-old boy with neuroblastoma stage IV (intermediate-risk group, negative MYCN amplification, negative 1p deletion) was referred to our department." (PMID 37466795, 2023). "The present study demonstrates that blocking selenium/selenocysteine uptake mechanisms could be an attractive indirect strategy to disrupt GPX4 function specifically and selectively to induce ferroptotic cell death in MYCN‐amplified neuroblastoma." (PMID 37435859, 2023). "Next, we examined whether #5333 and #5338 treatment for 48 h affected the levels of WS6 target proteins, PA2G4, and MYCN in neuroblastoma cells." (PMID 36980710, 2023). "Additionally, we performed GSEA for the comparison of PDΔATRX models with five non-MYCN amplified neuroblastoma cell lines (for number of DEGs see S2 Table) and for the comparison of neuroblastoma tumors from the individualized THERapy (iTHER) project." (PMID 37540673, 2023). "We found that the rates of MYCN gene amplification, the chromosome 1p36 and 11q deletion were 34%, 38.3% and 36.2%, respectively, which is in general agreement with other reports on pediatric neuroblastoma." (PMID 37035169, 2023). "In addition, manual curation highlighted ATF4 upregulation in MYCN-amplified compared to non-MYCN-amplified neuroblastoma cell lines, even with less induction (FC 1.77, p-value 0.047)." (PMID 37835497, 2023).
neuroblastoma (continued). "Hence, DLX1 is tagged by MYCN binding, a profile that mechanistically is in line with its transcriptional upregulation in MYCN-amplified neuroblastoma cells." (PMID 37835497, 2023). "In the neuroblastoma datasets, we investigated, the previously reported prognostic factors—age, MYCN amplification, and INSS stage 4 disease—were consistently associated with worse overall survival, but we did not observe a significant difference in NE scores in groups stratified by these factors." (PMID 37255415, 2023). "Interestingly, the human neuroblastomas expressing high levels of LMO3 in cluster 2h are enriched for neuroblastomas with MYCN gene amplification (cluster 2i)." (PMID 37183825, 2023). "MYCN has been widely studied as an oncogene that is amplified in pediatric neuroblastoma, but it is also expressed in some B cell lymphomas, a subset of T cell acute lymphoblastic leukemias (T-ALL), erythroleukemias, and leukemia cells lines including Jurkat T lymphoblasts." (PMID 36768931, 2023). "Reducing N-MYC levels in a neuroblastoma model with tunable MYCN expression mitigated cell death induction upon inhibition of mitochondrial translation and functionally validated the propensity of neuroblastoma cells for MYC-dependent cell death in response to the mitochondrial ISR." (PMID 37973789, 2023). "MYCN was identified as a paralog of c-MYC in neuroblastoma cell lines and tumor tissues." (PMID 37046804, 2023). "In this way, LIN28B promotes transformation and migration in colon cancer through LGR5, PROM1, and CDX2 mRNAs, promotes stemness and EMT in gastric cancer through NRP-1 mRNA, inhibits apoptosis in ovarian cancer through AKT2 mRNA, and promotes migration in neuroblastoma through MYCN-induced mRNAs." (PMID 37370851, 2023). "Of note, c-MYC, a paralog of MYCN, was almost not expressed in our neuroblastoma cohort, independent of the risk-group." (PMID 37402719, 2023). "Our findings further indicate that BAP1 could be a potential therapeutic target for MYCN-amplified neuroblastoma." (PMID 37543638, 2023). "Knockout of lmo1 in zebrafish reduces the penetrance of MYCN-induced neuroblastoma." (PMID 37183825, 2023). "Dysregulated MYCN is sufficient to form aberrant oncogenic SEs in neuroblastoma." (PMID 37415185, 2023). "The findings revealed that 12% to 26% of high-risk neuroblastoma tumors, including several MYCN-Amp tumors, had low TERT expression and no ALT activation." (PMID 36860927, 2023). "Apart from these murine neuroblastoma, a few MYCN-driven brain tumor models have been described." (PMID 38001143, 2023). "Similarly, a 350 ~ 2000 kb genome region carries the MYCN oncogene and its similarly amplified SEs in neuroblastoma, leading to high MYCN expression and driving carcinogenesis." (PMID 37501079, 2023). "The fact that around 50% of the neuroblastoma patients show metastasis with MYCN amplifications at diagnosis indicate that this oncogene might have a significant role in promoting metastasis." (PMID 37274289, 2023). "Next, they investigated if MYCN inhibition could also regulate the VEGF expression in neuroblastoma cells." (PMID 37274289, 2023). "For example, adrenal neuroblastomas are more frequently MYCN-amplified and are often in tumor stage 4 (International Neuroblastoma Staging System Committee (INSS) system), in which the primary tumor has spread to distant organs, compared with extra-adrenal neuroblastomas." (PMID 37361539, 2023). "Likewise, THZ1 suppresses MYCN gene expression in neuroblastoma, consequently disrupting the MYCN-regulated transcriptome." (PMID 37201585, 2023). "Hence the idea would be to achieve similar outcomes as dual Aurora-A and ATR inhibition and the profound effect that has on apoptosis of MYCN-amplified neuroblastoma tumours." (PMID 37414143, 2023).
neuroblastoma (continued). "However, the role of this mechanism in MYCN-amplified neuroblastoma is not yet fully understood and there are also data attributing a tumor suppressor function to HIF2α in neuroblastoma." (PMID 37361539, 2023). "In particular, the compound massively reduced the migratory ability of HTLA-230 cells, characterized by MYCN amplification, resulting in less effectiveness towards neuroblastoma ACN cells lacking this mutation." (PMID 37298148, 2023). "However, the relation between miRNA and MYCN in inducing metastasis is few explored in neuroblastoma." (PMID 37274289, 2023). "The International Neuroblastoma Risk Group (INRG) classifies NB into three risk groups (low-risk, intermediate-risk, or high-risk) based on age (month), tumor grade, histological category, 11q distortion, differentiation, MYCN and ploidy." (PMID 38001404, 2023). "Moreover, the expression levels of ZNF436 were lower in neuroblastoma with MYCN amplification or age at diagnosis ≥ 18months, or in stage 4 neuroblastoma." (PMID 37904225, 2023). "Considering the clinical heterogeneity of unfavourable neuroblastomas attributed to segmental chromosome alterations, additional gene alterations offering a survival advantage to MYCN-driven neuroblastoma are likely continually generated by NHEJ repair machinery." (PMID 37240360, 2023). "The developed signature also retained its independent prognostic effect in multivariate analysis with clinicopathological variables, including age at diagnosis, MYCN amplification status, and INSS stage–all of which are used to varying degrees to stratify neuroblastoma patient risk." (PMID 37532697, 2023). "Multiple studies have demonstrated MYCN to function as an oncogenic driver in neuroblastoma." (PMID 37274289, 2023). "Because of that, MYCN has been extensively used for modelling neuroblastoma in mice." (PMID 37444423, 2023). "Importantly, expression of TrkA and TrkC is positively correlated with favorable biological features of neuroblastoma, whereas increased expression of TrkB and BDNF is associated with an unfavorable prognosis in patients concomitant with MYCN-amplification." (PMID 36831211, 2023). "Indeed, this MYCN dependence on mitotic dysregulation was seen in cell lines of established neuroblastoma, where genetic or chemical inhibitors of mitosis were selectively toxic when MYCN was over-expressed, leading to the induction of apoptosis." (PMID 37958555, 2023). "Notably, our analysis also reliably captured every canonical fusion and other clinically relevant markers (for example, MYCN amplification in neuroblastoma), while providing further detailed characterization of clinical findings in other cases." (PMID 36585449, 2023). "Notably, TH-MYCN mice, which exhibit spontaneous neuroblastoma development due to MYCN overexpression, showed a higher PMN-MDSC abundance compared to M-MDSC." (PMID 38087370, 2023). "Engagement and degradation of XIAP by ARTS mimetics is a novel targeting strategy for neuroblastoma that may be especially effective against MYCN-amplified disease with intrinsically high XIAP expression." (PMID 37874199, 2023). "It is also possible that the decreased tumor initiation of neuroblastoma in lmo1–/– or TATA/TATA zebrafish in our MYCN-driven neuroblastoma model may reflect a role of lmo1 function in normal development of the PSNS." (PMID 37183825, 2023). "Here, we investigated whether DNA-PK inhibitor (DNA-PKi) could inhibit the proliferation of spheroids derived from neuroblastomas of MYCN transgenic mice and MYCN-amplified neuroblastoma cell lines." (PMID 37240360, 2023). "Genes involved in neuroblastoma, such as MYCN or CD44, are among them." (PMID 36675105, 2023). "A similar mechanism may also apply to neuroblastoma, where the dependence on MYCN to epigenetically sustain NE lineage could explain the high MYCN levels observed in samples with high NE scores." (PMID 37255415, 2023).
neuroblastoma (continued). "MYCN is a member of the MYC proto-oncogene family, which also includes MYC and MYCL, and encodes a basic helix–loop–helix–leucine zipper (bHLH–LZ) TF, initially characterized in neuroblastoma." (PMID 37835497, 2023). "Importantly, IRAK3 deficient mice showed enhanced response to PD-1 blockade in an ICB-refractory MYCN-driven neuroblastoma tumor model." (PMID 36757800, 2023). "It was also found that in trophically stressed neuroblastoma cells, overexpression of MYCN could weaken the anti-apoptotic effect of Bcl-2 and increase the cell death." (PMID 37543638, 2023). "Patients NB-008 and NB-009 were both diagnosed with neuroblastoma with high amplification of MYCN." (PMID 37189699, 2023). "Together our results support that MYCN globally downregulates circRNA levels in neuroblastoma." (PMID 37402719, 2023). "However, recent reports have shown that there is a subgroup of patients with stage 4S neuroblastoma characterized by MYCN amplification, chromosomal aberrations, age of < 2 months at diagnosis, and significantly poorer outcomes." (PMID 37286818, 2023). "The DRB1*15:01-DQA1*01:02-DQB1*06:02 haplotype was widely underrepresented, particularly in aRMS, osteosarcoma, neuroblastoma (MYCN-NA, MYCN-A, 11qWT), nephroblastoma, GBM and medulloblastoma (freq 0.038 to 0.073, RA 0.31 to 0.58) but overrepresented in eRMS (freq." (PMID 38318504, 2023). "We explored the link between MYCN amplification and global circRNA downregulation in more detail by comparing differentially expressed genes in high-risk neuroblastomas with or without MYCN amplification." (PMID 37402719, 2023). "Therefore, the role of LIN28B in neuroblastoma initiation and its correlation with MYCN expression makes it an important therapeutic target for intervention." (PMID 37274289, 2023). "Notably, LIG4 was identified as one of the worst prognostic factors in patients with MYCN-amplified neuroblastomas." (PMID 37240360, 2023). "The most downregulated circRNAs in the cell model were highly enriched among the top 500 downregulated circRNAs in MYCN-amplified neuroblastomas (p < 1e−16), thus showing in total that the MYCN-inducible cell model was able to reproduce the findings in the patient tumors." (PMID 37402719, 2023). "Epigenetic modifiers could be attractive drugs to restore a microenvironment more permissive for immune responses in MYCN-amplified neuroblastoma." (PMID 36923280, 2022). "Immunoblottingshows that VDR and MYCN are expressed in neuroblastoma cell-lines." (PMID 35404047, 2022). "Based on the overexpression of folate receptors on the surface of neuroblastoma cells, folate nanoliposome delivery system, a low-toxic and high specificity nanomaterial, was utilized for encapsulating MYCN-siRNA to achieve MYCN-specific interference in tumor tissues and promotion of cell apoptosis." (PMID 35721107, 2022). "In MYCN-related mice models, phosphatidylinositol 3-kinase (PI3K)/mTOR pathway inhibition is reported to destabilize N-Myc and be effective against tumors, while other studies have reported that N-Myc could regulate the mTOR pathway in neuroblastoma." (PMID 35490242, 2022). "Neuroblastoma cells may suffer genetic damage; the MYCN gene is a proto-oncogene that is amplified in more than 10 copies in 20–30% of cases, and it was associated with aggressive disease and poor outcome." (PMID 36360435, 2022). "In addition to MYCN-amplification states, neuroblastoma tumors display varying degrees of differentiation and have different sets of somatically acquired mutations." (PMID 36077650, 2022). "Brequinar was highly effective in MYCN-driven neuroblastoma models in vivo." (PMID 35943801, 2022). "Similarly, reports have also indicated that HSS increases the migration speed and directional migration of neuroblastoma IMR32 cells via regulating the MYCN protein." (PMID 36335301, 2022). "MYCN amplification and MYCN high expression represent adverse prognostic factors in neuroblastoma." (PMID 35764946, 2022).
neuroblastoma (continued). "Similarly, an RNAi screening identified CHK1 depletion as synthetic lethal with MYCN overexpression in neuroblastoma cells." (PMID 36214609, 2022). "Furthermore, inducible ablation of GPX4 in vivo suppressed the growth of MYCN‐amplified neuroblastomas." (PMID 35908258, 2022). "Similarly, knockdown MYCN promotes neuronal differentiation in neuroblastoma, and retinoic acid, which induces morphological differentiation of neuroblastoma cells, inhibits the expression of MYCN in these tumor cells." (PMID 34625907, 2022). "The MYCN oncogene is considered as a major oncogenic driver of neuroblastoma." (PMID 35053227, 2022). "PLK-1, CDK-1, PIK3CA, ATF4, TEAD4 and ALYREF could enhance MYCN protein stability and sustain MYCN expression in neuroblastoma." (PMID 35820898, 2022). "Interestingly, the highest levels of DHODH expression were observed in high-risk, MYCN-amplified tumors, and DHODH expression increased with International Neuroblastoma Staging System (INSS) stage." (PMID 35943801, 2022). "Taken together, these results may indicate that MYCN-driven neuroblastoma cells are less capable of pyrimidine salvage and more dependent on de novo pyrimidine biosynthesis via DHODH." (PMID 35943801, 2022). "Interestingly, blocking PI3K by SF1126 in neuroblastoma led to reduced MYCN expression, cell death and angiogenesis block, while temporarily increasing the macrophages’ M1 to M2 ratio, showing how all these mechanisms are interconnected." (PMID 36139583, 2022). "In addition, CCCTC-binding factor (CTCF) cooperates with noncoding RNA MYCNOS to promote neuroblastoma progression through facilitating MYCN expression." (PMID 36539767, 2022). "Likewise, CTH inhibition exerted more ferroptosis‐sensitizing effects on MYCN‐high adrenergic neuroblastoma cells than on MYCN‐high mesenchymal neuroblastoma cells." (PMID 35908258, 2022). "Bromodomain and extra-terminal domain (BET) protein inhibitor JQ1 has recently been reported to improve the survival in pre-clinical neuroblastoma mouse models, impact several cellular pathways, including MYCN expression, and impair hypoxic responses in triple-negative breast cancer." (PMID 36139358, 2022). "Furthermore, compared with classical parameters, here we showed that the survival of neuroblastoma patients can be more efficiently predicted by combining mTOR activity, MYCN-status, and differentiation." (PMID 35490242, 2022). "Interestingly, cultured mouse chromaffin cells show a sensitivity to BET inhibition caused by JQ1 and GSK132 (EC50 ≈ 50 nM), which is in the same range as the one observed for neuroblastoma cell lines, including cell lines with MYCN amplification." (PMID 35681734, 2022). "Furthermore, a functional enrichment analysis using predicted mRNA target genes from the 25 highly expressed exo-miRs from MYCN-amplified neuroblastoma cell lines revealed pathways related to cell growth, development, survival, and death." (PMID 36793342, 2022). "Indeed, MYCN amplified neuroblastoma cell lines fail to differentiate in response to 13-cis-retinoic acid." (PMID 36139583, 2022). "JQ1, the first developed BET inhibitor, could efficiently suppress the expression of MYCN in neuroblastoma by inhibiting the binding of BRD4 with acetyl lysine of histone." (PMID 36187481, 2022). "In neuroblastoma (NB) patients, the MYCN, as the potential biomarker, could predict the therapeutic efficacy susceptibility of NK cell‐mediated immunotherapy." (PMID 35150083, 2022). "MYCN is a major determinant of outcome in neuroblastoma, amplified in the most aggressive tumors." (PMID 34522028, 2022). "Moreover, ASCT2 knockdown induced G1 arrest and apoptosis in MYCN-amplified neuroblastoma cell lines and significantly inhibited their ability to form a tumor in immunodeficient mice." (PMID 36077650, 2022).